Y_RNA (Y RNA )
Gene: Miscellaneous RNA gene on chromosome 9 (34,389,943 to 34,390,051, reverse strand). Ensembl gene ENSG00000207032.
Homologues: Orthologues: chimpanzee Y_RNA (100% identical), macaque Y_RNA (95% identical), guinea pig Y_RNA (86% identical), dog Y_RNA (83% identical). Paralogues in human: RNY1 (89% identical), Y_RNA (89% identical), Y_RNA (88% identical), Y_RNA (87% identical), Y_RNA (86% identical), RNY1P11 (85% identical), Y_RNA (85% identical), Y_RNA (84% identical), RNY1P8 (83% identical), Y_RNA (83% identical), RNY1P7 (83% identical), Y_RNA (82% identical), and 101 more.